FGF23 (fibroblast growth factor 23)
Diseases named in the same sentence as FGF23 in open-access papers (continued):
Sharing a sentence is not in itself a finding about the gene and the disease.
Arrhythmia (11 papers, 2018 to 2026). Any cardiac rhythm other than the normal sinus rhythm. "In stage 5 CKD patients, FGF23 levels are independently associated with decreased heart rate variability, a predictive marker of cardiac arrhythmias." (PMID 30200452, 2018). "In addition, they found that FGF23 can induce a prolonged QTc interval, suggesting that FGF23 may increase the risk of arrhythmia by affecting the repolarization process of cardiomyocytes." (PMID 40126903, 2025). "Our results support FGF23 as a promoting factor of cardiac arrhythmias related to prolonged QT interval." (PMID 35042527, 2022). "In fact, CV events e.g., cardiac arrest and arrhythmia, are the leading cause of death in children with CKD and a dysregulated FGF23 metabolism may additionally have detrimental effects on the cardiovascular system." (PMID 34422725, 2021). "However, the relationship between imbalanced FGF23-Klotho axis and the development of cardiac arrhythmias in CKD remains unknown." (PMID 35042527, 2022). "Finally, according to some reports, all effects of FGF23 on the heart may not be that harmful; FGF23 may increase intracellular calcium in cardiac myocytes, promoting contractility, although this may contribute to a higher risk of arrhythmia." (PMID 30909513, 2019). "Experimental studies demonstrated direct detrimental cardiac effects of FGF23 including LVH, cardiac fibrosis, cardiac mechanical dysfunction and cardiac arrhythmias." (PMID 30200452, 2018). "Characterization of the receptors and molecular pathways by which FGF23 might mediate LVH, cardiac fibrosis, and arrhythmias will help to identify therapeutic targets." (PMID 32212912, 2020).
breast carcinoma (11 papers, 2017 to 2024). "Breast cancer may be associated with oncogenic osteomalacia and raised FGF23 levels." (PMID 33520985, 2020). "Previous studies have shown its expression alterations in breast cancer and identified that serum or plasma FGF23 concentrations are elevated in patients with advanced stage epithellal ovarian cancer." (PMID 37388244, 2023). "According to a phase 0/1 clinical trial, combined aromatase and FGFR1 inhibition in breast cancer results in a surge in the FGF23 plasma concentration." (PMID 33520985, 2020). "FGF23 mRNA expression is high in breast cancer cells, and FGF produced by tumor cells contributes to metastatic lesions." (PMID 33520985, 2020). "The combination of nintedanib (200 mg/bid) plus letrozole (2.5 mg/d) effectively inhibited both FGFR1 and aromatase in breast cancer patients, as evidenced by plasma FGF23 and 17-B-estradiol levels." (PMID 31126332, 2019). "FGF23 can be also produced by malignancies including colon adenocarcinoma, ovarian cancer, small cell carcinoma of the lung, anaplastic thyroid carcinoma, B-cell non-Hodgkin lymphoma, breast cancer, and intracranial tumours." (PMID 38397231, 2024). "FGF23 mRNA expression was high in breast cancer cells as well." (PMID 36926025, 2023). "This study has some limitations: (i) it is a small retrospective analysis of a prospective cohort, thus subject to residual confounding; (ii) it included different tumor types (being breast cancer the most predominant); and (iii) expression of FGF23 in metastatic tissue was not assessed." (PMID 30736285, 2019).
hereditary hypophosphatemic rickets (11 papers, 2009 to 2024). Hypophosphatemic rickets is a group of genetic diseases characterized by hypophosphatemia, rickets, and normal serum levels of calcium. "The second group involves genetic disorders of excessive renal phosphate loss (hereditary hypophosphatemic rickets) due to impairment in renal tubular phosphate reabsorption as a result of FGF23-related or FGF23-independent causes." (PMID 29280738, 2017). "Hereditary hypophosphatemic rickets and tumor-induced osteomalacia could by then be explained, by autonomous FGF23 production, and the nephrology field was excited by this new marker as it turned out to be independently associated with mortality in people treated by hemodialysis." (PMID 35665817, 2023).
Hyperglycemia (11 papers, 2015 to 2026). An increased concentration of glucose in the blood. "It is important to mention that most other FGF family members (such as FGF21 and FGF23) have been widely reported for their association with hyperglycemia, whereas research on FGF4 remains relatively limited." (PMID 41347806, 2026). "Theoretically, initiation of insulin therapy in patients with new onset T1D should not only increase sKlotho concentration by reducing hyperglycemia, but also by down-regulating FGF23 production." (PMID 34603200, 2021). "Thus, to avoid a potential confounding effect of hyperglycemia on FGF23 and phosphate metabolism, all the following experiments were performed on mice aged between 3 and 6 months." (PMID 34149625, 2021). "Additionally, the relationships between serum OCN, FGF23 and NGAL levels with visceral obesity still persisted among subjects with hyperglycaemia (P < 0.05)." (PMID 30424752, 2018). "Feeding a HF diet for 45 days did not increase body weight but elicited hyperglycemia, hypertriglyceridemia, an increase in plasma fibroblast growth factor 23 and a reduction in plasma calcitriol concentrations." (PMID 29281993, 2017). "In addition, serum FGF23 levels were elevated in obese individuals, especially those with visceral obesity, and this relationship was not affected by hyperglycaemia." (PMID 30424752, 2018).
phosphaturic mesenchymal tumor (11 papers, 2014 to 2026). An extremely rare, benign or malignant mesenchymal tumor arising from the soft tissues or bones. "Phosphaturic mesenchymal tumors (PMTs) are rare tumors that can cause tumor-induced osteomalacia (TIO) through overproduction of FGF23, a peptide hormone that causes renal phosphate wasting and reduced osteoblastic activity." (PMID 38455709, 2024). "Most FGF23-producing tumors associated with TIO are histologically called phosphaturic mesenchymal tumor, mixed connective tissue variant (PMTMCT)." (PMID 30627598, 2019). "Phosphaturic mesenchymal tumors (PMTs) are rare neoplasms that are often associated with tumor-induced osteomalacia (TIO) due to excessive serum levels of fibroblast growth factor 23 (FGF23)." (PMID 26956379, 2016). "Tumor-induced osteomalacia (TIO) is a rare paraneoplastic syndrome resulting from excessive secretion of fibroblast growth factor-23 (FGF23) by phosphaturic mesenchymal tumors (PMTs)." (PMID 42077462, 2026). "Phosphaturic mesenchymal tumors (PMTs) are rare neoplasms causing tumor-induced osteomalacia (TIO), usually through fibroblast growth factor 23 (FGF-23) secretion." (PMID 41182108, 2025). "Tumor-induced osteomalacia (TIO) is a rare paraneoplastic syndrome caused by the overproduction of fibroblast growth factor 23 (FGF23) secreted by phosphaturic mesenchymal tumors (PMTs)." (PMID 35693311, 2022). "Phosphaturic mesenchymal tumor (PMT) is an extremely rare neoplasm that causes tumor-induced osteomalacia (TIO) in most affected patients, usually through the production of fibroblast growth factor 23 (FGF23)." (PMID 36686800, 2022).
enthesopathy (10 papers, 2019 to 2025). "Increasing 1,25D action by treatment of Hyp mice with 1,25D or FGF23Ab prevents the increase in BMP and IHH and, thus, enthesopathy, despite increased Fgf23 mRNA expression in bone and serum FGF23 levels." (PMID 37490334, 2023). "Treatment of mice with XLH (Hyp) with 1,25D or an anti–FGF23 Ab, both of which increase 1,25D signaling, prevents enthesopathy." (PMID 37490334, 2023). "Treatment of Hyp mice with daily 1,25D or an Ab targeting FGF23 (FGF23Ab), which increases 1,25D levels, prevented enthesopathy in Hyp mice despite dramatic increases in Fgf23 expression." (PMID 37490334, 2023). "Indeed, transgenic mice overexpressing the secreted form of human FGF23 exhibit enthesopathy, and entheseal fibrochondrocytes are known to express the FGFR3 receptor as well as the Klotho coreceptor, which promotes FGF23 signaling." (PMID 37871131, 2024). "Taken together, our results demonstrate that in XLH, impaired 1,25D action due to high serum levels of FGF23, not the direct effects of increased FGF23, underlies the pathogenesis of enthesopathy." (PMID 37490334, 2023). "In addition to determining a role for impaired 1,25D signaling due to enhanced FGF23 levels in XLH enthesopathy development, these studies will also define a role for 1,25D in normal postnatal enthesis maturation." (PMID 37490334, 2023). "Mouse models suggested that FGF23 itself might be directly involved in enthesopathy and that mineralization of entheses might be exacerbated by treating with calcitriol and phosphate." (PMID 32374835, 2020). "Analysis of entheses in mice null for both Cyp27b1 and Fgf23 (C–/–F–/–), which have normal serum calcium and phosphate levels when fed a rescue diet, will differentiate whether impaired 1,25D production due to high FGF23 levels or actions specific to FGF23 lead to XLH enthesopathy." (PMID 37490334, 2023). "Enthesopathies are also commonly observed in other phosphate-wasting disorders of excessive FGF23 (ARHR1, AHRH2), and in murine models of XLH (Hyp, Fgf23-TG)." (PMID 30808384, 2019). "Taken together, these results support our hypothesis that the impaired 1,25D action due to increased FGF23 levels in Hyp mice contributes to the enhanced BMP and IHH signaling observed in Hyp mice and, thus, to enthesopathy development." (PMID 37490334, 2023). "Because both treatments attenuated Hyp enthesopathy despite dramatic increases in Fgf23 expression, these studies implicate impaired 1,25D action due to the high serum levels of FGF23 in XLH rather than direct effects of increased circulating FGF23 in the pathogenesis of XLH enthesopathy." (PMID 37490334, 2023). "Specifically, there currently are no data to determine whether anti-FGF23 antibody therapy (such as with burosumab) might have any effect to slow the progression of enthesopathy." (PMID 32374835, 2020). "Although the effects of FGF23 blocking on enthesopathies have not specifically been assessed, significant improvements have been observed in treated XLH patients scored on the Western Ontario and McMaster Universities Osteoarthritis Index (WOMAC), which focuses on patient perception of joint pain." (PMID 30808384, 2019). "However, the means by which elevated FGF23 and/or reduced phosphate may induce enthesopathy is not clear." (PMID 37871131, 2024). "Because FGF23 overexpression is unlikely to be the only consequence of the PHEX mutation, ablation of both Cyp27b1 and Fgf23 in Hyp mice (C–/–F–/–/Hyp) will further elucidate if 1,25D- and FGF23-independent effects of the PHEX mutation influence XLH enthesopathy pathogenesis." (PMID 37490334, 2023).
cardiomyopathy (9 papers, 2015 to 2025). A disease of the heart muscle or myocardium proper. "Another study analyzed the association of serum FGF23 and Klotho in the progression of 287 patients with chronic heart failure (CHF) and cardiomyopathy (CMP) as the etiology." (PMID 39330350, 2024). "In summary, FGF23 plays an important role in CKD-related cardiomyopathy, and myocardial FGFR4 blockade appears to be a promising therapeutic target for it prevention." (PMID 30087898, 2018). "Serum levels of sKlotho and FGF23 were measured in 287 patients with cardiomyopathy (CMP)." (PMID 29849175, 2018). "The next evolutionary step in our FGF23 understanding was the transfer from association toward causality: Recent experimental data established a causal pathway and linked extra-cardiac FGF-23 directly to the development of cardiovascular pathologies, specifically cardiomyopathy." (PMID 30013515, 2018). "A recent noteworthy study showed that a decreased level of circulating sKlotho in CKD mice is an important cause of uremic cardiomyopathy independent of FGF23 and phosphate and that intravenous delivery of a transgene encoding sKlotho ameliorated the cardiomyopathy." (PMID 26604925, 2015). "sKL may be a risk factor for cardiomyopathy in uremic patients, independent of FGF23 and phosphate." (PMID 34079811, 2021).
carotid atherosclerosis (9 papers, 2015 to 2025). A thickening and loss of elasticity of the walls of carotid arteries that occur with formation of atherosclerotic plaques. "Further research, including larger validation cohorts and prospective data about clinical outcomes, is needed to clarify the role of FGF-23 as a marker and potentially also a mediator and novel therapeutic target in carotid atherosclerosis." (PMID 38711510, 2024). "In patients with acute IS, the plasma FGF23 concentration was positively correlated with the presence and burden of intracranial carotid atherosclerosis." (PMID 33424930, 2020). "Moreover, elevated serum FGF23 levels and FGF23/α-klotho ratio were positively associated with CIMT and carotid atherosclerosis in T2DM patients (all P values < 0.01)." (PMID 38622690, 2024). "Indeed, in a population-based study, individuals with increased FGF-23 levels had a more significant burden of carotid atherosclerosis independent of CKD." (PMID 38711510, 2024). "In this retrospective observational study, we analyzed FGF23 serum level in 361 type 2 diabetic patients with internal carotid artery stenosis undergoing carotid endarterectomy and in 598 diabetic controls without carotid atherosclerosis." (PMID 26459301, 2015).
chronic obstructive pulmonary disease (9 papers, 2018 to 2025). A chronic and progressive lung disorder characterized by the loss of elasticity of the bronchial tree and the air sacs, destruction of the air sacs wall, thickening of the bronchial wall, and mucous accumulation in the bronchial tree. "Chronic obstructive pulmonary disease (COPD) is associated with the downregulation of Klotho expression in the airways and an increase in circulating FGF23 levels." (PMID 32188018, 2020). "Our recent data characterized FGF23 signaling as an important mediator in inflammatory airway diseases such as cystic fibrosis and chronic obstructive pulmonary disease (COPD)." (PMID 30538676, 2018). "FGF23 may also play a pro-inflammatory role in chronic obstructive pulmonary disease (COPD), as elevated levels of this hormone have been demonstrated in COPD patients compared to a control group." (PMID 40862708, 2025). "It has also been speculated that FGF23 might serve as a biomarker for chronic obstructive pulmonary disease, and smokers have elevated serum FGF23 levels, indicating that FGF23 might be involved in a wider spectrum of chronic lung disorders." (PMID 29770125, 2018). "Chronic obstructive pulmonary disease (COPD) has been reported to elevate circulating FGF23 levels independently of renal status." (PMID 40869274, 2025). "In patients with chronic obstructive pulmonary disease (COPD) and cystic fibrosis, serum FGF23 levels are significantly elevated." (PMID 31461904, 2019).
cognitive decline (9 papers, 2016 to 2025). "But in the survival curve, we found that patients with high FGF-23 levels have a lower risk of cognitive decline later in life." (PMID 40950978, 2025). "Elevated FGF23 levels have also been associated with an increased risk of silent brain infarcts and embolic infarcts, both of which are associated with cognitive decline [1045, 1052]." (PMID 40407975, 2025). "Future studies are essential to clarify whether FGF23 directly drives cognitive decline and vascular aging or if its elevation reflects underlying metabolic or vascular pathologies." (PMID 40407975, 2025). "FGF23 is also associated with alcohol abuse, and increased FGF23 beyond normal physiological threshold values causes an alteration in hippocampal morphology, and a cognitive decline." (PMID 30868037, 2019). "Analysis of all dialysis-induced cognitive decline cases revealed that the area under the ROC curve for α-klotho, FGF-23, IL-6, TNF-α, BDNF, BMI, and calcium were 0.58, 0.55, 0.58, 0.59, 0.70, 0.64, and 0.62, respectively." (PMID 40950978, 2025). "The average FGF-23 levels were found to be higher in patients with cognitive decline, indicating a significant difference (p < 0.05)." (PMID 40950978, 2025). "Receiver operating characteristic (ROC) curves demonstrated that FGF-23 was a potential biomarker for diagnosing cognitive decline in hemodialysis patients." (PMID 40950978, 2025). "Furthermore, we observed that the levels of fibroblast growth factor (FGF-23) in MHD patients with cognitive decline were significantly higher than those in the normal cognitive group." (PMID 40950978, 2025). "The best cutoff values for serum α-klotho, FGF-23, IL-6, TNF-α, BDNF, BMI, and calcium levels for the diagnosis of dialysis-induced cognitive decline were 469.5 pg/mL, 1,264.5 ng/mL, 1.8 pg/mL, 21.1 pg/mL, 20.0 ng/mL, 23.9 kg/m2, and 2.52 mmol/L, respectively." (PMID 40950978, 2025). "Understanding the contributions of osteocalcin, FGF23, and LCN- 2 to cerebrovascular aging and cognitive decline may provide novel therapeutic targets for combating age-related diseases." (PMID 40407975, 2025).
McCune-Albright syndrome (9 papers, 2012 to 2026). McCune-Albright syndrome (MAS) is classically defined by the clinical triad of fibrous dysplasia of bone (FD), cafe-au-lait skin spots, and precocious puberty (PP). "Burosumab, a humanized monoclonal antibody for FGF23 which will increase renal tubular reabsorption of phosphate represents a promising treatment option for hypophosphatemic osteomalacia in McCune-Albright syndrome, however further clinical trials are needed to establish standardized protocols." (PMID 40357201, 2025).
metabolic acidosis (9 papers, 2014 to 2025). "We also noted that patients with metabolic acidosis tend to exhibit lower FGF-23 at a given eGFR and serum phosphorus level." (PMID 25659076, 2015). "Six months post-KTx, 6 (32%) patients still present with metabolic acidosis, 10 (53%) persistent hyperparathyroidism (always < 2 ULN), and 5 (26%) elevated FGF23 levels; 11 (58%) received phosphate supplementation." (PMID 39384649, 2024).
Osteopenia (9 papers, 2015 to 2025). Osteopenia is a term to define bone density that is not normal but also not as low as osteoporosis. "In particular the only significative difference is observed in osteoporotic patients, displaying higher bone fragility, while at the level of osteopenia the risk of fracture is still too low to induce a marked and significative increase of FGF23." (PMID 28630637, 2017). "cKO mice exhibited increased osteocytic expression of Sost, Fgf23 and senescence inducing gene Pai-1 and the senescence markers p16 and Il-6, decreased serum phosphate levels, and low-turnover osteopenia." (PMID 37198221, 2023). "Although our data do not provide a final mechanistic explanation for these observations, we could exclude PTH and FGF23 as hormonal mediators of HF-induced osteopenia." (PMID 41515999, 2025). "In line with the hypothesis that FGF23 may be involved in the pathogenesis of TAC-induced osteopenia, we observed an increase in osteoid maturation time in vertebral cancellous bone of TAC mice." (PMID 41515999, 2025).